NCAPH (non-SMC condensin I complex subunit H)
Description:
Regulatory subunit of the condensin complex, a complex required for conversion of interphase chromatin into mitotic-like condense chromosomes. The condensin complex probably introduces positive supercoils into relaxed DNA in the presence of type I topoisomerases and converts nicked DNA into positive knotted forms in the presence of type II topoisomerases. Early in neurogenesis, may play an essential role to ensure accurate mitotic chromosome condensation in neuron stem cells, ultimately affecting neuron pool and cortex size.
Synonyms: hCAP-H; BRRN1; CAPH; CAP-H; NCAPH1; MCPH23
Tractability: PROTAC: UniProt records ubiquitination sites on it; ubiquitination databases record sites on it.
Gene: Protein-coding gene on chromosome 2 (96,335,734 to 96,377,091, forward strand). Ensembl gene ENSG00000121152.
Subcellular location: Nucleus; Cytoplasm; Chromosome
Subcellular location (Human Protein Atlas): Cytosol; Nucleoplasm; Vesicles
Pathways (Reactome):
Cell Cycle: Condensation of Prometaphase Chromosomes
Gene Ontology:
Molecular function: protein binding; chromatin binding
Biological process: mitotic chromosome condensation; positive regulation of chromosome condensation; B cell differentiation; cell development; female meiosis chromosome separation; female meiotic nuclear division; immunoglobulin heavy chain V-D-J recombination; positive regulation of chromosome segregation; positive regulation of chromosome separation
Cellular component: condensin complex; cytosol; membrane; nucleoplasm; chromosome; condensed nuclear chromosome; cytoplasm; nucleus
Genetic constraint (gnomAD): Loss-of-function variants: 32 observed, 75.89 expected, observed/expected ratio (o/e) 0.42, 90% interval 0.32 to 0.57. The upper end of that interval is the gene's LOEUF score, 0.57, which puts it in group 2 of 6, group 1 being the genes least tolerant of losing a copy. Missense variants: 746 observed, 879.51 expected, observed/expected ratio (o/e) 0.85, 90% interval 0.8 to 0.9. Synonymous variants: 284 observed, 327 expected, observed/expected ratio (o/e) 0.87, 90% interval 0.79 to 0.96.
Homologues: Orthologues: chimpanzee NCAPH (99% identical), macaque NCAPH (97% identical), pig NCAPH (85% identical), dog NCAPH (84% identical), rabbit NCAPH (83% identical), guinea pig NCAPH (80% identical), rat Ncaph (79% identical), mouse Ncaph (78% identical), tropical clawed frog ncaph (55% identical), zebrafish ncaph (45% identical), Drosophila melanogaster barr (22% identical).
Diseases named in the same sentence as NCAPH in open-access papers:
NCAPH is named in the same sentence as 62 diseases in open-access papers, as found by Europe PMC text mining. Sharing a sentence is not in itself a finding about the gene and the disease. The quoted sentences say what the papers report.
breast carcinoma (14 papers, 2013 to 2025). "The intratumoural levels of these transcripts, akin to NCAPH itself, were also associated with the adverse progression of luminal breast cancer in both mice and humans." (PMID 38344872, 2024). "In this cohort of mice, we identified a series of transcripts associated with elevated intratumoral levels of NCAPH, which were linked to adverse progression of breast cancer in both mice and humans." (PMID 37886490, 2023). "Moreover, the putative potentiation of estrogen signalling by NCAPH helps explain the hyperplasia observed in transgenic mice overexpressing NCAPH and their increased susceptibility to breast cancer development." (PMID 38344872, 2024). "Notably, the overexpression of NCAPH leads to an enlargement of the non‐tumourous breast's glandular component, a recognised factor predisposing to breast cancer." (PMID 38344872, 2024). "Furthermore, we reveal that a signature of intratumoral gene expression, associated with elevated levels of NCAPH, serves as a potential marker to identify patients facing unfavorable progression of luminal A breast cancer." (PMID 37886490, 2023). "Moreover, an NCAPH‐associated signature defines the outcome of the luminal A breast cancer subtype." (PMID 38344872, 2024). "After demonstrating that NCAPH is involved in breast cancer development and is linked to poor prognosis in breast cancer, we aimed to identify the specific intrinsic subtype of breast cancer where intratumoural NCAPH levels are associated with unfavourable outcomes." (PMID 38344872, 2024). "Elevated levels of NCAPH expression have been observed in tissues from patients with breast cancer 39, prostate cancer 40 and endometrial cancer 41 compared to normal tissues." (PMID 41210692, 2025). "NCAPH has been shown to promote the malignant progression of many cancers, such as breast cancer, bladder cancer, and colorectal cancer." (PMID 38587786, 2025). "In the present work, we substantially broaden the research on NCAPH's role in breast cancer development." (PMID 38344872, 2024). "Since elevated NCAPH levels mediate a poor response to chemotherapy in breast cancer patients and cells, we evaluated the response of tumours generated in BX‐Neu+ mice to chemotherapy." (PMID 38344872, 2024). "Here, we demonstrate that NCAPH participates in the pathogenesis of breast cancer and in chemotherapy resistance in vivo and in vitro." (PMID 38344872, 2024). "Our findings suggest that NCAPH overexpression can eventually act as a primary oncogenic trigger for breast cancer." (PMID 38344872, 2024). "Collectively, our discoveries substantially augment the current understanding of NCAPH's role in the onset and progression of breast cancer." (PMID 38344872, 2024). "Takuya also found that OCT1 is a poor prognostic factor for breast cancer patients and promotes cell proliferation via inducing NCAPH." (PMID 38605354, 2024). "In this study, we demonstrate that NCAPH plays a role in the pathogenesis of luminal A breast cancer, contributing to its adverse progression in vitro and in vivo." (PMID 37886490, 2023). "We showed that OCT1 promotes the proliferation of breast cancer cells by inducing a cell cycle transition from the G1 phase to the S phase, which was a similar target of action to NCAPH." (PMID 34768935, 2021). "To investigate the biological functions of NCAPH in breast cancer cells, we performed the knockdown of NCAPH using siRNAs (siNCAPH #1, siNCAPH #2) in MCF-7 cells and LTED cells." (PMID 34768935, 2021). "Then, we compared endogenous NCAPH expression in the human breast cancer cell line MCF-7 and LTED cells." (PMID 34768935, 2021). "Since information on the roles of NCAPH in breast cancer was limited, we further analyzed the clinical value of NCAPH." (PMID 34768935, 2021). "In contrast, our data suggest that NCAPH promotes the transition from the G1 to the S phase in breast cancer cells." (PMID 34768935, 2021).
breast carcinoma (continued). "In cervical cancer and breast cancer, NCAPH can induce the tumorigenesis through PI3K/AKT pathway." (PMID 38587786, 2025). "To ascertain that elevated levels of NCAPH were associated with a diminished response to chemotherapy, we engineered an MCF7 luminal A breast cancer cell line wherein NCAPH overexpression could be triggered by doxycycline." (PMID 38344872, 2024). "In conclusion, we have demonstrated that NCAPH is involved in the pathogenesis of breast cancer." (PMID 38344872, 2024). "Consequently, this prompted us to investigate the potential involvement of NCAPH in the pathogenesis of breast cancer." (PMID 38344872, 2024). "We found that NCAPH contributes to adverse luminal A breast cancer progression." (PMID 38344872, 2024). "Thus, to analyse the contribution of NCAPH expression to the heterogeneous outcome of luminal ERBB2 breast cancer, we used a genetically heterogeneous cohort of MMTV‐ErbB2 transgenic mice generated by backcrossing (BX‐Neu+ mice after that)." (PMID 38344872, 2024). "The knockdown of NCAPH has also been shown to reduce breast cancer cell proliferation." (PMID 39346787, 2024). "Thus, elevated levels of NCAPH promote a more aggressive form of breast cancer, potentially elucidating the adverse progression observed in luminal tumours." (PMID 38344872, 2024). "Similarly, NCAPH can be used as a prognostic biomarker for non-small cell lung cancer, lung adenocarcinoma, nasopharyngeal carcinoma, breast cancer, and hepatocellular carcinoma." (PMID 37192046, 2023). "We demonstrated that the knockdown of NCAPH suppressed the proliferation of breast cancer cells." (PMID 34768935, 2021). "Our data showing a higher expression level of NCAPH in LTED cells compared to MCF-7 cells may suggest that NCAPH is related to endocrine resistance in breast cancer." (PMID 34768935, 2021). "In the present study, we showed that the silencing OCT1 or NCAPH suppressed the proliferation of MCF-7 and LTED cells, which suggests that OCT1 and NCAPH could be potential targets for breast cancer therapy." (PMID 34768935, 2021). "Consequently, we explored if NCAPH levels could differentiate between prognostically favourable and unfavourable forms within each intrinsic breast cancer subtype." (PMID 38344872, 2024). "Notably, while NCAPH transgenic mice developed distinct histopathological types of breast cancer, the MMTV‐NCAPHErBb2 double‐transgenic mice developed only infiltrating ductal adenocarcinomas, suggesting that the ErbB2 oncogene exerts a dominant effect on the tumour phenotype." (PMID 38344872, 2024). "Recent studies have demonstrated that NCAPH silencing significantly downregulates the AKT/mTOR signaling pathway, thereby inhibiting proliferation, migration, and invasion in breast cancer cells." (PMID 39991770, 2025). "Previous research has demonstrated that poor prognosis is correlated to abnormal condensin complex I expression of the NCAPH, NCAPG, and NCAPD2 subunits in NSCLC, liver cancer, colorectal cancer, breast cancer, and prostate cancer." (PMID 38566039, 2024). "Hence, the overexpression of NCAPH could drive breast cancer development." (PMID 38344872, 2024). "NCAPH expression is upregulated in HNSCC, gastrointestinal cancer, hepatocellular carcinoma (HCC), lung cancer, breast cancer, prostate cancer, and renal cell carcinoma compared with its levels in the normal mucosa according to TCGA data analysis." (PMID 31892156, 2019). "To determine whether NCAPH is a driver of breast cancer development, we generated transgenic mice overexpressing NCAPH under the control of the MMTV promoter, inducing NCAPH overexpression in the mammary gland." (PMID 38344872, 2024). "Among these genes, we focused on NCAPH, of which no functional analysis in breast cancer has been reported so far to the best of our knowledge." (PMID 34768935, 2021).
breast carcinoma (continued). "We could speculate that the high expression of NCAPH predicts poor prognosis for breast cancer patients because the expression of NCAPH was not suppressed by endocrine therapy." (PMID 34768935, 2021). "Since luminal HER2 tumours are not defined as an intrinsic subtype of breast cancer defined by PAM50, immunohistochemical classification was used to define the role of NCAPH in the prognosis of this tumour subtype." (PMID 38344872, 2024).
cervical cancer (8 papers, 2020 to 2026). A primary or metastatic malignant neoplasm involving the cervix. "In 607 cases of cervical cancer, one case had NCAPH amplification, three cases had missense mutation." (PMID 33311486, 2020). "Therefore, NCAPH is a novel autophagy-associated protein that plays an important role in the regulation of autophagy in cervical cancer." (PMID 39103348, 2024). "The expression of NCAPH has consistently been associated with lymph node metastasis in our cervical cancer patients indicating that NCAPH might facilitate tumor invasion and metastasis by promoting EMT." (PMID 33311486, 2020). "In cervical cancer, NCAPH is significantly upregulated, correlating with tumor size, invasion, and LN metastasis." (PMID 39543244, 2025). "For instance, by forming regenerative feedback with human papilloma virus E7 (HPV E7), upregulated NCAPH enhances the proliferation ability of cervical cancer cells through stimulating the PI3K/AKT/SGK pathway." (PMID 38587786, 2025). "Immunohistochemical staining revealed that the protein expression of TRIM21 was negatively correlated with that of NCAPH and positively correlated with that of beclin-1 in cervical cancer tissues." (PMID 39103348, 2024). "Previously, we identified NCAPH as a new oncoprotein able to promote cervical carcinogenesis by increasing the proliferation of cervical cancer cells." (PMID 39103348, 2024). "Previously, we identified NCAPH as a novel oncoprotein involved in the occurrence and development of cervical cancer." (PMID 39103348, 2024). "To further verify the correlation between TRIM21, NCAPH and autophagy, we performed a bioinformatics analysis in cervical cancer." (PMID 39103348, 2024). "Consistent with in vitro findings, TRIM21 expression was negatively correlated with that of NCAPH, but positively with Beclin-1 in cervical cancer patients." (PMID 39103348, 2024). "Different from previous studies, the mRNA level of E7 decreased significantly when we knocked down NCAPH in cervical cancer cells." (PMID 33311486, 2020). "We used cBioPortal to study the genetic changes of NCAPH gene in all the two cervical cancer studies." (PMID 33311486, 2020). "In conclusion, our results revealed the role of NCAPH in the carcinogenesis of cervical cancer in vitro and in vivo." (PMID 33311486, 2020). "Real-time PCR and Western blot analysis revealed that mRNA and protein levels of NCAPH significantly decreased with the knockdown of E2F1 or increased with the over-expression of E2F1 in cervical cancer cells (all the p values < 0.05)." (PMID 33311486, 2020). "In summary, we report that NCAPH is a novel oncogene that plays an important role in the initiation and progression of cervical cancer." (PMID 33311486, 2020). "The expression of NCAPH in cervical cancer was significantly higher than in normal cervix (p < 0.001) and HSIL (p = 0.004) separately." (PMID 33311486, 2020). "To evaluate the biological function of NCAPH in cervical cancer, we designed three pairs of specific siRNAs targeting NCAPH gene, and assessed their interference efficiency in cervical cancer cell lines HeLa and SiHa." (PMID 33311486, 2020). "To explore the role of NCAPH in cervical cancer in vivo, we first determined the NCAPH mRNA level in 10 cases of normal cervical tissues and 22 cases of invasive cervical squamous cell carcinoma (ICSCC) tissues by real-time quantitative PCR." (PMID 33311486, 2020). "To determine the effects of NCAPH on the migration and invasion of cervical cancer cells, we performed transwell assays." (PMID 33311486, 2020). "The data from cBioportal database revealed that NCAPH was significantly co-expressed with PDK1 in cervical cancer specimens." (PMID 33311486, 2020). "The formation mechanism of feedback loop between HPV E7 and NCAPH deepens the molecular mechanism of HPV induced cervical cancer, and expands the mechanism of trans-regulation of host protein to HPV genes." (PMID 33311486, 2020).
cervical cancer (continued). "Consistent with it, NCAPH was significantly co-expressed with PCNA (a specific marker for proliferation ability) in 308 cases of cervical cancer patients from the cBioportal database." (PMID 33311486, 2020). "We confirmed the relationship between NCAPH expression and clinicopathological parameters and prognosis of cervical cancer patients." (PMID 33311486, 2020). "We next investigated the relationship between the expression of NCAPH and the clinicopathological parameters of cervical cancer patients." (PMID 33311486, 2020). "In this study, we have shown that silencing NCAPH expression reduced the proliferation, invasion, migration, and xenograft tumor formation ability of cervical cancer cells in vitro and in vivo." (PMID 33311486, 2020). "The mRNA level of NCAPH in cervical cancer tissues was significantly higher than that in normal cervical tissues (p < 0.05)." (PMID 33311486, 2020). "In another study on cervical cancer, it was shown that AP-1 could affect the PI3K signaling pathway by regulating HPV E7-mediated NCAPH expression, thereby enhancing the proliferation and survival of cervical cancer cells." (PMID 41158757, 2026). "Here, we found that NCAPH was a novel target protein of the E3 ligase TRIM21 in cervical cancer." (PMID 39103348, 2024). "However, interference with NCAPH expression significantly increased autophagic body formation and promoted the autophagic flow process in cervical cancer." (PMID 39103348, 2024). "To determine whether the RING domain of the TRIM21 protein mediates the degradation of NCAPH in cervical cancer, we transfected HeLa and SiHa cells with a full-length TRIM21 plasmid (HA-TRIM21) and a RING domain-mutated plasmid (TRIM21 ΔRING)." (PMID 39103348, 2024). "Therefore, TRIM21 promoted autophagy in cervical cancer by inhibiting NCAPH and the downstream AKT/mTOR pathway." (PMID 39103348, 2024). "In our study, we elucidated that TRIM21 could inhibit autophagy by regulating the expression of NCAPH in cervical cancer cells." (PMID 39103348, 2024). "To further confirm these results, we performed immunohistochemical staining and found that TRIM21 was overexpressed in 129 patients with cervical cancer (129/220, 58.64%), NCAPH was overexpressed in 84 patients (84/220, 38.18%), and beclin-1 was overexpressed in 156 patients (156/220, 70.91%)." (PMID 39103348, 2024). "Therefore, the regulatory role of NCAPH in autophagy is achieved mainly through its regulation of the stage of autophagic body formation in cervical cancer cells." (PMID 39103348, 2024). "It is worthy of note that NCAPH can regulate the PI3K/AKT signaling pathway in cervical cancer." (PMID 34399777, 2021). "Moreover, NCAPH expression in cervical cancer was significantly higher than those in normal cervix and HSIL." (PMID 33311486, 2020). "Receiver operating characteristic curves demonstrated that NCAPH expression could clearly separate normal cervix and cervical cancer cases, with the area under curve of 0.8826 (p = 0.0006)." (PMID 33311486, 2020). "To unravel whether AP-1 participates in NCAPH-mediated LCR activation, we investigated the component changes of AP-1 transcription factor after interference with NCAPH in cervical cancer cells." (PMID 33311486, 2020). "Thus, both in vitro and in vivo results showed that NCAPH plays a vital role in the regulation of EMT processes in cervical cancer." (PMID 33311486, 2020). "NCAPH might regulate E7 gene transcription by enhancing the activity of viral promoter in cervical cancer cells." (PMID 33311486, 2020). "It is known that HPV genome is integrated into host chromosome in cervical cancer cells, however it is unclear whether NCAPH regulates E7 through host or viral promoters." (PMID 33311486, 2020). "In our study, we assessed the expression of NCAPH in human cervical cancer tissues." (PMID 33311486, 2020).